GCG (glucagon)
Diseases named in the same sentence as GCG in open-access papers (continued):
Sharing a sentence is not in itself a finding about the gene and the disease.
Hypoglycemia (continued). "Furthermore, patient-reported outcomes, hypoglycemia episodes, and biomarkers such as postprandial glucagon levels were tracked." (PMID 39273299, 2024). "Here, we show that, in addition to insulins, the deadly fish hunter, Conus geographus, uses a selective somatostatin receptor 2 (SSTR2) agonist that blocks the release of the insulin-counteracting hormone glucagon, thereby exacerbating insulin-induced hypoglycemia in prey." (PMID 39164229, 2024). "Fourth, excessive and inappropriate use of insulin, which may result in hypoglycemia, can further induce insulin resistance by stimulating the secretion of counter-regulatory hormones, mainly glucagon, along with catecholamines, cortisol, and growth hormone." (PMID 39003471, 2024). "In conclusion, a novel glucose-responsivepolymer-GCG conjugatesystem was developed that self-assembled into micelles under normoglycemicconditions via reversible binding of phenylboronicacid units to glucose and disassembled during hypoglycemia, releasingthe active glucagon conjugate." (PMID 39634211, 2024). "Several mechanisms are known to prevent hypoglycemia, namely, reduced secretion of insulin from beta cells, reduced absorption of glucose in peripheral tissues, raised releasing of glucagon from α-cells, raised level of glucose, and a stimulated adrenal medulla." (PMID 38094502, 2023). "Indeed, during energy deficit LEAP-2 has been reported to decline in effort to raise blood glucose for the prevention of hypoglycemia via a potential influence of glucagon mediated hepatic glucose production." (PMID 36771362, 2023). "Surprisingly, plasma glucose increased significantly more upon glucagon challenge in the group of rats in which hypoglycaemia was induced using GCGRi–insulin (p<0.001), and plasma glucose was elevated for a longer time compared with animals in which hypoglycaemia was induced using HI." (PMID 36404376, 2023). "Typically, glucagon reverses hypoglycemia; however, in patients with pancreatogenic diabetes, a small insulin overdose resulting in hypoglycemia may be life-threatening." (PMID 36945494, 2023). "Moreover, several GPR119 agonists have been reported to enhance glucagon secretion during hypoglycemia in ex vivo and in vivo experiments." (PMID 36462626, 2023). "Hypoglycaemia treatment counselling was predominantly about carrying glucose tabs; there was no counselling about what steps to take after the initial treatment of a hypoglycemic event, or about glucagon use." (PMID 38076413, 2023). "GIP-mediated increase in circulating glucagon concentrations has been detected also in healthy humans, similar to preclinical studies this effect is glucose dependent, as it has been shown to occur only under hypoglycemia." (PMID 37729025, 2023). "Besides the intestine, liver, kidney, and pancreatic β cells, GLUT2 is also expressed in the central nervous system (CNS), which senses glucagon induced by hypoglycemia to regulate blood glucose." (PMID 37358764, 2023). "Hypoglycemia may stimulate the secretion of counter-regulatory hormones, such as glucagon, epinephrine, and cortisol, leading to rebound hyperglycemia after dialysis." (PMID 37089609, 2023). "As in GHD, the biochemical features in infants are identical to those of hyperinsulinism (hypoglycemia associated with low/normal levels of ketone bodies and fatty acids, absence of metabolic acidosis and positive response to glucagon administration)." (PMID 37630734, 2023). "Intervention studies could help to target specific needs of patients and parents concerning their hypoglycemia and glucagon training." (PMID 37628318, 2023). "Thus, the action of mini-doses of glucagon was blunted after an insulin bolus but preserved for hypoglycemia during low circulating insulin levels." (PMID 37334295, 2023). "Protein intake also stimulates insulin secretion but does not cause hypoglycemia, possibly because protein intake stimulates glucagon, which facilitates glycogenolysis in the liver." (PMID 38068304, 2023).
Hypoglycemia (continued). "Furthermore, we found compensatory increased glucagon secretion in those with hypoglycaemia, in contrast to what has been reported previously." (PMID 37720541, 2023). "Another possible explanation for postprandial hypoglycemia is glucagon resistance." (PMID 37635984, 2023). "Moreover, CFTR gene mutations exert an influence on glucagon secretion from pancreatic alpha cells, manifesting as reduced glucagon levels and an inadequate response to arginine stimulation or hypoglycemia." (PMID 38136081, 2023). "However, despite the increased abundance of α cells, glucagon secretion (like insulin secretion) is impaired in CF, in response to a range of stimuli including arginine and hypoglycemia." (PMID 38075070, 2023). "Indeed, as a first-line defence against hypoglycaemia, glucagon secretion is rapid in response to hypoglycaemia and is facilitated by several α-cell morphological features." (PMID 37159865, 2023). "We previously showed that lower hepatic glycogen content was associated with diminished glucagon and HGP responses to insulin-induced hypoglycemia in dogs, but the impact of liver glycogen content on islet hormone levels and HGP was not evaluated under euglycemic conditions." (PMID 37166980, 2023). "Moreover, results confirmed good levels of confidence among scholastic personnel who participated in the training of administration of glucagon in case of severe hypoglycaemia." (PMID 38239792, 2023). "Since glucagon, which is utilized as a treatment for clinical hypoglycemia, raises blood glucose levels, supplementation with glucagon may prevent SRH." (PMID 37367911, 2023). "Those with hypoglycaemia had higher 60-min glucose, 120-min C-peptide, and 180-min glucagon levels (27.8% [11.3-46.7%], 42.9% [5.9-92.85%], and 80.3% [14.9-182.9%], respectively) and unaltered proinsulin-to-insulin ratio compared to those without hypoglycaemia." (PMID 37720541, 2023). "Incipient hypoglycemia triggers a cascade of protective responses, including the suppression of endogenous insulin, stimulation of glucagon secretion, and sympatho-adrenal activation, thus increasing endogenous glucose production and reducing glucose disposal to restore normal glycemia levels." (PMID 37327258, 2023). "The majority of cells were A, alpha cells that secrete glucagon (a polypeptide hormone secreted in response to hypoglycemia or growth hormone stimulation); or B, beta cells that secrete insulin into the bloodstream in response to a rise in concentration of blood glucose or amino acids." (PMID 37663296, 2023). "Moreover, in T1DM, after 2–4 years of disease onset, the ability to increase glucagon secretion (the main counterregulatory hormone) in response to hypoglycemia is permanently and completely abolished." (PMID 37998439, 2023). "Mini-glucagon 19-29 has a potent limiting effect on insulin secretion and it could happen that RYGB modifies the released ratios of glucagon/mini-glucagon 19-29, which could explain the episodes of postprandial hypoglycemia." (PMID 37635984, 2023). "Among the five participants with no detectable C-peptide levels in the blood, ablated counter-regulatory responses to hypoglycemia were restored by administering subjects 600 mg of GABA for 11 days, which augmented glucagon, epinephrine, and growth hormone in response to hypoglycemia." (PMID 37296593, 2023). "The primary outcome was the incremental AUC of glucagon during hypoglycaemia." (PMID 36648553, 2023). "C-peptide may protect against hypoglycemia by increasing α-cell response to low blood sugar and promoting glucagon secretion." (PMID 37745697, 2023). "In contrast, individuals with type 1 diabetes are unable to regulate their own insulin levels following subcutaneous delivery, and they often exhibit diminished glucagon and epinephrine responses to hypoglycemia, thereby making them much more vulnerable to low blood glucose." (PMID 37166980, 2023). "For example, self-injections of glucagon are indicated to treat hypoglycemia." (PMID 37629010, 2023).
Hypoglycemia (continued). "Additionally, further studies are needed to improve training on hypoglycemia management and glucagon administration." (PMID 37628318, 2023). "In addition, a complete glucagon response to hypoglycemia relies on positive autocrine feedback mediated by extracellular glutamate, which acts on ionotropic glutamate receptors of the AMPA/kainite type." (PMID 38168840, 2023). "Furthermore, data confirmed the extreme ease of use of nasal glucagon, which helped to increase teachers’ self-confidence in the use of this drug in case of severe hypoglycaemia." (PMID 38239792, 2023). "Relatively reduced glucagon levels contribute to hypoglycemia unawareness, prolonged hypoglycemia and increased glycaemic variability whereas, hyperglucagonemia provides better hypoglycemia awareness at the cost of postprandial hyperglycemia and increased glycaemic variability." (PMID 35819935, 2022). "In contrast, the glucagon counterregulatory response to neuroglycopenia was attenuated in mice fed a ketogenic diet for 21 days, suggesting a differential effect of nutritional ketosis on the components of hypoglycemia counterregulatory response." (PMID 36676967, 2022). "Our study began with the unexpected observation that Klf15−/− mice, despite having chronic hypoglycemia and substantially elevated plasma glucagon concentration, had inappropriately low plasma concentration of total corticosterone, the predominant circulating corticosteroid hormone in mice." (PMID 35263131, 2022). "SC bihormonal artificial pancreas devices that utilise both insulin and glucagon can potentially allow more aggressive insulin treatment than unihormonal devices using only insulin, as glucagon could counteract insulin-induced hypoglycaemia." (PMID 36213069, 2022). "The MiRNA levels altered by hypoglycemia reflected changes in counter-regulatory glucagon and differed between cohorts, and their expression at 24 h suggests miRNAs may potentiate and prolong the physiological response." (PMID 36499023, 2022). "Likewise, deletion of ACC1 in alpha-cells in mice reduced glucagon secretion at low glucose in isolated islets, and in response to fasting or insulin-induced hypoglycaemia in vivo." (PMID 35304577, 2022). "In a following study, the authors further revealed that recurrent hypoglycemia enhances GABAergic inhibitory tone in the VMH, which contributes to the impairment of CRR (i.e., reduction in glucagon and epinephrine release) to subsequent bouts of acute hypoglycemia." (PMID 35619170, 2022). "When compared to carbohydrate ingestion, administering low-dose glucagon before exercise may result in less post-exercise hypoglycemia." (PMID 35345701, 2022). "The hypoglycemia‐activated glucagon booster release from the GRS glucagon MN patch was validated on two groups of diabetic mice: one exhibiting hyperglycemic PGLs (untreated) and one undergoing hypoglycemic PGLs (treated with 15 h‐fasting and a subcutaneous injection of 75 μg kg−1 insulin)." (PMID 35957510, 2022). "Meanwhile, GPR40 activation stimulates glucagon secretion to prevent hypoglycemia." (PMID 36246919, 2022). "* The cause of deficient or nonexistent release of glucagon in response to hypoglycemia in individuals with T1D relates to something that is within the islet cells of the pancreas." (PMID 36992764, 2022). "Furthermore, hypoglycemia induced by i.p. insulin injection or during a hypoglycemic clamp led to lower glucagon secretion in AgRPAgpat5KO than in control mice." (PMID 36180454, 2022). "Furthermore, Cpt1aflox/flox mice and AgRPCpt1aKO littermates displayed identical glucose tolerance, insulin sensitivity, and glucagon response to insulin-induced hypoglycemia." (PMID 36180454, 2022). "Higher glucagon in MET-treated patients may be protective against hypoglycemia that is a feared complication of DM treatment and was linked to arrhythmias and increased mortality." (PMID 35906276, 2022).
Hypoglycemia (continued). "However, insulin-induced hypoglycemia after NA pre-treatment led to the same plasma glucagon levels in Agpat5flox/flox mice and AgRPAgpat5KO mice." (PMID 36180454, 2022). "As our own screen was based on insulin-induced hypoglycemia Agpat5 could, in principle, mediate its effect on glucagon secretion by controlling insulin sensitivity and hypoglycemia development and/or on hypoglycemia sensing." (PMID 36180454, 2022). "The simultaneous AA-induced increase in plasma glucagon levels and insulin levels allows both insulin-induced energy-consuming processes to coincide with the processes of glycogenolysis or gluconeogenesis to prevent hypoglycemia." (PMID 35448534, 2022). "We initially suspected that increased production of insulin or a failure to produce glucagon might be the basis of hypoglycemia." (PMID 36548717, 2022). "Indeed, reduced glucagon secretion in response to hypoglycemia and increased post-prandial glucagon secretion are frequently found in T1D patients." (PMID 36277717, 2022). "In addition to the main controller focusing on insulin infusion, a fuzzy logic fusion controller was introduced to infuse glucagon based on the identified signals during a hypoglycemia event." (PMID 35200143, 2022). "Here, we investigated the role of Agpat5 as a regulator of hypoglycemia-induced glucagon secretion." (PMID 36180454, 2022). "In hypoglycemia glucagon is secreted from the pancreatic alpha cell." (PMID 36686477, 2022). "This may involve multiple compounding factors and underlying mechanisms, such as the secondary messenger system via glucagon and epinephrine release and cortisol and growth hormone release that counteract hypoglycemia." (PMID 35203750, 2022). "A positive correlation of glucagon levels with MAGE and GV-hyperglycemia variables in patients with FCPD and hypoglycemia awareness, further suggested that increased glucagon levels may play a key role in modulating hyperglycemia associated GV in this group." (PMID 35819935, 2022). "Experiments in rat models of diabetes are suggestive of impaired counter-regulatory glucagon secretion during insulin-induced hypoglycaemia due to increased somatostatin signalling, the effects of which can be reversed by somatostatin receptor 2 antagonism (SSTR2a)." (PMID 36147573, 2022). "It is well known that GH, together with glucagon, cortisol, and epinephrine, display counterregulatory actions protecting from hypoglycemia, and that its excess may have a diabetogenic role as seen in subjects suffering from acromegaly." (PMID 35265043, 2022). "Thus, reduced AgRP activation by hypoglycemia in AgRPAgpat5KO mice led to impaired vagal nerve firing and reduced glucagon secretion." (PMID 36180454, 2022). "Glucagon’s ability to increase blood glucose concentrations seems to be influenced by the concentration of circulating insulin, and it is most effective in situations with impending hypoglycaemia and low systemic insulin concentrations." (PMID 36213069, 2022). "As glucagon works to mobilize stored energy by acutely stimulating glycogenolysis or gluconeogenesis in the liver, it is released from the pancreatic alpha cells in response to hypoglycemia." (PMID 35456307, 2022). "In addition, they directly stimulate α-cells to produce more glucagon in response to hypoglycemia and decrease insulin secretion." (PMID 35346357, 2022). "Patients with feeding problems require intravenous glucagon infusions due to severe hypoglycemia." (PMID 36294341, 2022). "As a hypothesis, this observation may be due to increased glutaminolysis by the action of glucagon to stimulate mitochondrial anaplerotic flux in the setting of hypoglycemia, feeding the pool of glutamate (and α‐ketoglutarate)." (PMID 34671989, 2022). "For instance, the recommendation to prescribe glucagon for patients at risk of episodes of hypoglycemia, a life-saving medical standard in developed countries, was excluded due to the lack of availability of glucagon in Pakistan." (PMID 36686436, 2022).
Hypoglycemia (continued). "The primary rationale for dual-hormone systems, which are capable of administering boluses of glucagon in addition to continuous insulin infusion, is that prevention of hypoglycemia is more effective with administration of glucagon than with suspension of insulin delivery." (PMID 35733769, 2022). "At 16 h glucagon expression was significantly decreased, despite the developing hypoglycemia." (PMID 36548717, 2022). "We map out the early stages of our hypothesis as a disruptive novel approach, where we propose to use glucagon as a vasodilator to accelerate the absorption of meal boluses of insulin, besides using it conventionally to treat hypoglycaemia." (PMID 36213069, 2022). "Apart from preventing postabsorptive hypoglycemia, AA-induced glucagon secretion may also play a role in modulating hepatic gluconeogenesis during fasting, which increases the plasma concentration of various AAs." (PMID 35448534, 2022). "Based on the ability of V1bRs to promote glucagon release, we explored the possibility that V1bR signaling contributes to the counterregulatory increase in plasma glucagon levels triggered by insulin-induced hypoglycemia." (PMID 34752420, 2021). "In response to hypoglycemia (blood glucose of 2.8±0.1 mM), plasma glucagon increased by >300%." (PMID 34787082, 2021). "In contrast, the catecholamine adrenaline is a body’s soluble signal that has a clear differential effect on two major islet cells subpopulations: it inhibits secretion of insulin by β-cells and induces secretion of glucagon from α-cells to rescue extreme hypoglycemia." (PMID 34460580, 2021). "In addition, glucagon response to insulin‐induced hypoglycemia is impaired soon after the development of T1D, presenting further challenges to maintain tight glucose control." (PMID 34027090, 2021). "We first explored the role of AVP during hypoglycemia, a potent stimulus of glucagon secretion." (PMID 34787082, 2021). "Moreover, glucagon response to insulin-induced hypoglycemia is suppressed during pregnancy potentially due to decreased pancreatic islet sensitivity to the action of glucagon." (PMID 34684381, 2021). "This includes blood glucose from hypoglycemia to hyperglycemia, osmolality, natremia, lipids, proteins, amino acids, and the hormones glucagon, GLP-1, leptin, and CCK." (PMID 33495245, 2021). "Moreover, C-peptide infusion during insulin-induced hypoglycemia doubled glucagon secretion and increased net hepatic glucose output by 75%, thereby lowering the need for exogenous glucose to maintain glycemia." (PMID 34003799, 2021). "They hypothesized that intrahepatic transplanted islets were enclosed by high levels of glucose released by glycogenolysis that could inhibit the glucagon response to hypoglycemia." (PMID 34067286, 2021). "We hypothesize that OGT plays a key role in the maintenance of α-cell mass and proper function of secreting glucagon in response to hypoglycemia." (PMID 33460647, 2021). "Moreover, C-peptide infusion also doubled glucagon secretion in these animals during insulin-induced hypoglycemia, which increased net HGP by 75% and lowered the need for exogenous glucose infusion." (PMID 34003799, 2021). "Glucagon action is critical for correcting hypoglycemia but other potent stimulators of glucagon secretion are high amino acid levels, which may be an even more effective stimulus than low blood glucose levels." (PMID 34382579, 2021). "Even more remarkable was that C-peptide’s effect on glucagon secretion was even more pronounced during hypoglycemia, leading to a 2-fold increase in glucagon secretion in the CPEP group compared with SAL, and a 75% increase in net HGP, which decreased the need for exogenous glucose infusion." (PMID 34003799, 2021). "In addition, adequate intervention requires education, especially since glucagon represents the mainstay of hypoglycemia treatment of in out-of-hospital environments." (PMID 34638984, 2021).